LGR5 (leucine rich repeat containing G protein-coupled receptor 5)
Diseases named in the same sentence as LGR5 in open-access papers (continued):
Sharing a sentence is not in itself a finding about the gene and the disease.
tumor (continued). "We also investigated the relationship between LGR5 and β-catenin expression related to LGR5 regulation, and that between CD8-positive tumor-infiltrating lymphocytes (CD8 + TILs) and LGR5 expression in immune responses." (PMID 32293346, 2020). "In tumor xenograph studies, SNC also reduced expression of Wnt target genes including CD44, Sox2 and LGR5." (PMID 33347461, 2020). "To functionally confirm that the anti-tumor effects of Arf1-depletion in Lgr5/Apc and MYC-ON mice were indeed dependent on the observed adaptive immune response, we depleted the T lymphocytes after tumor formation by injecting anti-CD4 or anti-CD8 antibodies." (PMID 31924786, 2020). "Two different anti-LGR5 monoclonal antibodies, 8F2 and 9G5, were evaluated using 89Zr immunoPET to select the optimal mAb for ADC development and tumor imaging." (PMID 33081383, 2020). "Positive correlations linking TCF7 with LEF1 and with LGR5 in normal tissue are reduced in tumor tissue, and the negative correlation between AXIN2 and TCF7L1 in normal tissue is also reduced in tumor tissue." (PMID 32403323, 2020). "Although the elevation of LGR5 expression and potential association with clinical outcome have been observed in HCC patients, whether it can serve as an independent prognostic biomarker remains to be further investigated in specifically designed tumor marker prognostic studies in patients." (PMID 32327656, 2020). "Lgr5 (leucine-rich-repeat containing G-protein-coupled receptor 5), a marker for ISC21, is also expressed in tumor-induced colon tissues of both humans and mice." (PMID 30996297, 2019). "Therefore, interactions between T helper cells and Lgr5+ stem cells may probably take place during the progression of tumor-promoting immune microenvironment of chronic inflammation due to their proximity, which may play critical roles in tumor growth and metastasis." (PMID 31358061, 2019). "Several transcription factors, including BMI1, LGR5, NANOG, OCT4, and SOX2, are upregulated in various cancer types and promote stemness maintenance, local tumor invasion, and distant metastasis." (PMID 30866999, 2019). "The leucine-rich repeat-containing G-protein-coupled receptor 5 (LGR-5) is a novel biomarker, particularly in stem cells, and is involved in embryogenesis, tumor development, and tumor cell signal transduction." (PMID 31126119, 2019). "For LGR5 and FZD7, the percentage of positive tumor cells varied between 0 and 100%, while the percentage of MIST1-positive tumor cells varied between 0 and 75%." (PMID 31827644, 2019). "Briefly, by regulating Wnt signaling, LGR5 is important for CIC maintenance and thereby tumor progression." (PMID 31921628, 2019). "Thus our results indicate that LGR5 might be involved in tumor progression and metastasis of OSCCs." (PMID 30770730, 2019). "Upon treatment of these tumours with anti-RSPO3 antibody using patient-derived xenograft models, expression of LGR5 and ASCL2 were highly downregulated, whereas MYC, AXIN2 and CCND1 (cyclin D1) did not rank among the top 100 downregulated genes." (PMID 30792270, 2019). "The fact that Notch1+ tumour cells present an expression profile very similar to the signature of Notch1+ ISCs, prompts us to speculate that Notch1+ tumour cells might derive from +4 ISCs, shown to express lower levels of Lgr5 than CBCs and paramount for intestinal regeneration." (PMID 30696875, 2019). "Lgr5 expression in SGC-7901 cells was enhanced by Tregs, following the incubation of tumor cells with 1 × 104 Tregs/mL Tregs for 36 h." (PMID 31417548, 2019). "The inverse correlation between WDR76 expression and LGR5 expression in murine and human CRCs emphasizes the pathological importance of WDR76 destabilizing RAS as a tumor suppressor inhibiting CSC activities." (PMID 31362761, 2019). "Proliferative Lgr5− cells attempt to replenish the Lgr5+ CSC pool in the TME and promote rapid re-initiation of tumor growth upon treatment cessation." (PMID 30841635, 2019).
tumor (continued). "This was also observed in vivo in HCT116 tumor xenograft model which showed a reduction in TCF4, β-catenin and LGR5 expression after γ-Mangostin treatment along with the reduced tumor volume and tumor weight." (PMID 31608135, 2019). "We further showed that high Lgr5 expression in CRC was positively correlated to the TB grade, suggesting the cancer stem cell features of those tumor budding cells in CRC." (PMID 30046385, 2018). "More recently, two independent approaches have shown LGR5+ cell ablation in human and mouse CRC organoid xenografts is sufficient to induce tumour remission, further supporting a ‘bottom-up’ CSC model for CRC." (PMID 29570681, 2018). "Wnt target genes were downregulated during CRC progression and several, including LGR5, were found to be methylated in both CRC cell lines and primary tumours." (PMID 29844449, 2018). "This review will focus on the regulation of epithelial stem cells by LGR5 and LGR6 and the contribution of this signaling pathway to tumor formation and chemoresistance." (PMID 29416699, 2018). "The tumor-initiating markers CD44, CD133 and LGR5 were markedly down-regulated after culture of IHCC organoids in DM in comparison to culture in EM." (PMID 29434290, 2018). "Meanwhile, the expression levels of LGR5 and c-myc were also increased in PIK3CA mutant tumor tissues comparing with wild type tumors Further immunobloting analysis was also performed with CC-1 cells." (PMID 29970892, 2018). "As a result, LGR5 and N-cadherin mRNA expression were significantly higher in HCC tissues than in those non-tumor tissues." (PMID 28881613, 2017). "Directing a lineage‐tracing cassette to the KRT20 locus to track differentiated cells demonstrated that KRT20+ cells can reverse into LGR5+ cells with TIC capacity upon LGR5+‐cell ablation, thereby driving tumor re‐growth." (PMID 28559443, 2017). "The mRNA expression of LGR5, N-cadherin and E-cadherin in HCC tissues were also compared with those in corresponding adjacent non-tumor tissues using real-time PCR." (PMID 28881613, 2017). "Our work shows that human LGR5+ CRC cells express the gene program of normal ISCs, are clonogenic ex vivo, and display robust tumor‐initiating capacity in xenograft assays." (PMID 28468934, 2017). "First, the kinetics of differentiation of tumor cells in CRC appears to be a relatively slow process compared to the normal epithelium, where the progeny of LGR5+ ISCs undergoes differentiation 2–3 days after they leave the crypt base." (PMID 28468934, 2017). "Several putative markers i.e., Musashi (Msi), CD44, CD133, leucine-rich repeat-containing G-protein-coupled receptor 5 (LGR5) and aldehyde dehydrogenase 1 (ALDH1) have been used to identify tumor stem-like cells in CRCs." (PMID 28484082, 2017). "Accordingly, loss of adenomatous polyposis coli (APC) elevates the nuclear accumulation of β-catenin in leucine-rich repeat-containing G-protein-coupled receptor 5 LGR5+ normal stem cells and triggers neoplasia by transforming these cells into CSCs." (PMID 28757546, 2017). "We also observed LGR5−/MUC2+ cells with goblet‐like morphology intermingled between LGR5+ and LGR5− compartments throughout the tumor." (PMID 28468934, 2017). "The results showed that Lgr5 high expression group had remarkably more patients with >60 years (p=0.001), male (p=0.024), macroscopic type III (p=0.030), tumor size 4cm-7cm (p=0.044) and TNM III stage (p=0.046) than Lgr5 low expression group." (PMID 27557490, 2016). "We found that, compared to unsorted control cells, CXCR4+/Lgr5-, Lgr5+/CXCR4- and Lgr5+/CXCR4+ Caco-2 and HT-29 cells generated significantly more tumor spheres." (PMID 27835894, 2016). "We previously reported that the expression of several cancer stemness-related genes such as PROM1 (CD133), GPR49 (Lgr5) and MUC15 was significantly higher in RR cells as compared to RU cells derived from BC cell lines as well as primary tumor samples." (PMID 26683522, 2016).
tumor (continued). "Instead, Lgr5-targeted, GLI2A-expressing epithelial cells in intestine appear to be eliminated through apoptosis prior to tumor development." (PMID 26859571, 2016). "The control, CXCR4+/Lgr5-, Lgr5+/CXCR4- and Lgr5+/CXCR4+ Caco-2 and HT-29 cells were subjected to tumor sphere formation assay." (PMID 27835894, 2016). "HCCs with microscopic vascular invasion had high mRNA levels of HAPLN1, LGR5, LEF1, SOX9, CD44, Glypican 3 and larger tumor size." (PMID 27191501, 2016). "Since knockdown of GATA6 resulted in a more significant inhibition of tumor growth than REG4 or LGR5 knockdown alone, we examined the effect of REG4 and LGR5 double knockdown on the tumorigenicity of HT29 cells." (PMID 26387746, 2015). "The correlation of Lgr5 expression with clinical-pathological features in CRC, such as tumor grade and tumor stage, was also investigated." (PMID 26674601, 2015). "The expression levels of LGR5, EPHB2, CD44s and CD44v6 were increased at least 2-fold in 70.8% (34/48), 72.0% (36/50), 66.0% (33/50) and 86.0% (43/50) of tumour tissues compared to matched normal tissues." (PMID 26367378, 2015). "As we have shown, the majority of the established CR4 cells, as well as a significant proportion of cells from NOD/SCID mice tumor xenografts induced by these cells, express high levels of CD133, CD44, CD166, EpCAM and Lgr5." (PMID 24921652, 2014). "Because the EMT has been shown to endow tumor cells stem-like properties 31,32, we next assayed the surface expression of CD44 and lgr5, which have been shown to be specific markers of GCSPCs 33–35." (PMID 25142304, 2014). "Compared to NM, LGR-5 was overexpressed in MDF and tumours (LI: 4.7±2.0 and 2.9±1.0 in MDF and tumours, respectively, P<0.01 compared to NM)." (PMID 23374535, 2013). "Analysis of LGR-5 expression was carried out in 13 MDF and 15 tumours as well in the adjacent normal mucosa (NM)." (PMID 23374535, 2013). "Based on these premises, in order to characterize the expression of putative stem markers during the early phases of carcinogenesis, we studied the expression of LGR-5, MSI-1, DCAMKL-1, CD133 and ALDH1-A1 in both MDF and tumours by immunohistochemistry." (PMID 23374535, 2013). "To verify this hypothesis we treated tumour-bearing rats for two weeks with celecoxib to determine if the treatment was able to reduce the percentage of cells with putative stemness features which we considered those expressing both LGR-5 and nuclear β-catenin." (PMID 23374535, 2013). "The LGR5+ colorectal CSC have increased clonogenic and tumorigenic potential compared to bulk tumor cells and lose expression of LGR5 upon in vitro differentiation." (PMID 23596566, 2013). "A significant post-therapeutic increase in NOTCH2, LGR5 and POU5F1 expression was found in tumours with different tumour regression grades." (PMID 22970250, 2012). "Our findings indicate that the quantitative molecular assessment of AGR2 and LGR5 can serve as a surrogate marker of CTC and ISC-like circulating tumor cells in CRC patients." (PMID 22605983, 2012). "IL-17RA overexpression significantly increased CSC marker expression, including cluster of differentiation 133 (CD133), leucine-rich repeat-containing G protein-coupled receptor 5 (LGR5), sex determining region Y-box 2 (SOX2), and enhanced tumor sphere formation and 5-FU resistance in SW620 cells." (PMID 41438576, 2026). "Furthermore, within tumor cell subsets, co-expression of ALKBH5 with LGR5 (R = 0.39, P < 0.0001; n = 1295 cells) and CD133 (R = 0.25, P < 0.0001; n = 2867 cells) were observed." (PMID 41390849, 2025). "A recent study using an inducible lineage-tracing system in CRC organoid xenografts has revealed that dormant LGR5+p27+ cells, anchored at the COL17A1-enriched matrix interface, persist in a drug-tolerant state during chemotherapy and later reinitiate tumor growth." (PMID 41002429, 2025).
tumor (continued). "The functional effect of LGR5 on tumor growth may be dependent on cancer type, TME and cross-talk with other molecules in LGR5 signaling pathway." (PMID 39821694, 2025). "While petosemtamab can bind independently to cells expressing only the LGR5 antigen, the ability to simultaneously bind EGFR can in principle facilitate enhanced avidity-driven binding to dual-target-expressing cells within a tumor." (PMID 40427162, 2025). "We also detected tumor stem cells by staining CD44 and Lgr5 markers." (PMID 40611658, 2025). "Similar to normal gut homeostasis, LGR5 is functionally redundant at certain stages of tumor growth, but at specific phases of tumor growth, especially during metastatic progression and drug/radiation exposure, LGR5 becomes essential and LGR5-CRC cells rapidly acquire LGR5 expression." (PMID 41194856, 2025). "mIHC was performed to simultaneously assess LGR5 and LAPTM4B expression in 71 CRC tumor samples." (PMID 40661135, 2025). "In a three-dimensional (3D) co-culture organoid model of primary murine liver tumors, the presence of CAFs significantly increased the number of LGR5+ TICs in the tumor compared to organoids lacking CAFs." (PMID 40568600, 2025). "Overall, LGR5 appears to exert a complex regulatory effect on immune infiltration, displaying both positive and negative associations, which suggests that it may modulate the immune composition of the tumor microenvironment rather than acting in a unidirectional manner." (PMID 41194856, 2025). "These included LGR5 as a stem cell and regeneration mRNA marker, SNAIL and TWIST1 as markers of epithelial–mesenchymal transition; and IL-8, CCL2, and COX2 as pro-inflammatory tumor microenvironment markers." (PMID 40476597, 2025). "Importantly, reduced mRNA expression of LGR5, OLFM4, ASCL2 and EPHB2 was also observed in HG primary tumours in the TCGA dataset." (PMID 40473896, 2025). "In preclinical models of human CRC, targeted depletion of the LGR5+ cells from a cancer does not fully eliminate the tumor mass, instead resulting in tumor stasis." (PMID 40427162, 2025). "Detection by staining against CD44 and Lgr5 demonstrated that all the tumoroids contained tumor stem cells, indicating that tumor stem cells in tumoroids were not influenced by 3DREs in our study." (PMID 40611658, 2025). "Similarly, the elimination of Lgr5+ CSCs with iCaspase 9 and Dimerizer triggers a shrinkage of tumor volume, accompanied by activation of KRT20+ differentiated cells and a large number of Lgr5− cells dedifferentiate into colonies." (PMID 39872442, 2024). "Additionally, Lgr5-GFP expression was found to be decreased after irradiation relative to the control group in both normal and tumor tissue." (PMID 39410012, 2024). "Moreover, it has been demonstrated that in tumors in which Lgr5+ cells are targeted, proliferative Lgr5– cells, via plasticity and dedifferentiation, restore the Lgr5+ CSC pool, leading to reinitiation of tumor growth." (PMID 39225547, 2024). "In fact, selective Lgr5+ cell ablation in vivo halts primary tumor growth, although targeting Lgr5+ CSCs has not been related to tumor regression." (PMID 39225547, 2024). "Interestingly, in this study the tumor-promoting and metastasis-inducing MACC1 is upregulated in LGR5+ stem cells of the mouse intestine." (PMID 39580452, 2024). "To determine whether the humanised α-LGR5 antibody could also be used therapeutically, we treated NALM6 tumour-bearing mice with two doses of 5 mg/kg α-LGR5v4-ADC or 5 mg/kg of the non-binding control α-LGR5v6-ADC on days 6 and 8 post tumour implantation (PI)." (PMID 39169164, 2024). "The tumor stem cell markers CD133 and Lgr5 were also significantly elevated (p < 0.01)." (PMID 39302044, 2024). "Thus, prognostic and functional studies of LGR5 expression in CRC and other malignancies indicate that elevated LGR5 expression in tumour cells is crucial for proliferation, marking LGR5 as a promising target for cancer treatment." (PMID 39169164, 2024).
tumor (continued). "Using α-LGR5 for analysing LGR5 protein expression in human tissues and cancers, we establish low to undetectable levels in healthy human tissues, and specific overexpression in CRC, HCC and pre-B-ALL tumours." (PMID 39169164, 2024). "Lgr5 is not distributed in chemical- and ultraviolet-induced epidermal tumors, nor does it participate in tumor maintenance." (PMID 39684417, 2024). "REG4 upregulation in the tumor may create additional cancer stem cell (CSC) niches, facilitating the growth of the aggressive subpopulation of LGR5-positive CSCs." (PMID 38066386, 2024). "Next, the in vitro experiments revealed that the tsRNA-GlyGCC inhibitor suppresses cell proliferation, migration, and formation of tumor spheres by modulating the protein expression of BCL2, BAX and cancer stem cells molecular markers (CD44,CD133, EphB2, LICAM, and LGR5)." (PMID 39153969, 2024). "We did not observe off-target toxicities in α-LGR5-ADC-treated mice; however, α-LGR5 does not cross-react with murine Lgr5, and it will be important to evaluate on-target, off-tumour toxicities in an appropriate model." (PMID 39169164, 2024). "Since CSCs are believed to be responsible for tumor metastasis and relapse, interventional combinatorial approaches targeting MACC1 and LGR5 will potentially improve further targeted therapies for CRC patients to eradicate CSCs and prevent cancer recurrence and distant metastasis formation." (PMID 38339354, 2024). "For instance, in xenograft mouse cancer organoids, gene knockout of LGR5+ CSCs can limit tumor growth but not eliminate it." (PMID 38965243, 2024). "There is also evidence of Lgr5-positive cell generation through Lgr5-negative tumor cell plastic transitions." (PMID 39456736, 2024). "We conclude that residual tumour load from treatment of tumour-bearing mice with α-LGR5-based therapeutics are the consequence of incomplete tumour access and targeting and not due to downregulation of LGR5 expression in tumour cells." (PMID 39169164, 2024). "Lgr5+ cells isolated from normal tissues, primary tumours, or metastases do not show any EMT features but are characterised by stem cell gene signatures." (PMID 37259089, 2023). "AMBL was found to express ABCG2, ALDH1, BMI1, CD133, CD166, CD44, and c-Myc in peripheral and/or central cells of the parenchyma at variable extent and intensity levels, as well as CD34 in spindle-shaped stomal cells and LGR5 and NANOG in both epithelial and stromal tumor components." (PMID 37761874, 2023). "Tumor growth and expression of CSC-related Wnt genes, including Lgr5 were decreased." (PMID 38140103, 2023). "Lgr5-EGFP fluorescence was absent in disseminated tumor cells (DTCs) and micrometastases, but was progressively gained during metastatic outgrowth, in a marked antithetic pattern to Emp1-TOM expression." (PMID 36352230, 2022). "Analysis of LGR5 and NANOG expression levels by RT-PCR in these tumors revealed that in mice inoculated with tumor cells expressing PC inhibitors, the level of NANOG was reduced by up to 60% and 40% in Spn4A and α1-PDX-expressing cells injected mice, respectively." (PMID 35267511, 2022). "Mirroring the observations in human tumor samples, we found that mouse CRCs contained abundant HRCs and that this population did not express the Lgr5+ ISC-like expression program." (PMID 36352230, 2022). "For each tumor, we generated multiple gene expression signature scores measuring MEK pathway activation, MEKi “bypass” resistance, SRC activation, dasatinib sensitivity, EMT, PC1, Hu-Lgr5-ISC, Hu-EphB2-ISC, Hu-Late TA, Hu-Proliferation, and WNT activity." (PMID 35272617, 2022).